ALB (albumin)
Diseases named in the same sentence as ALB in open-access papers (continued):
Sharing a sentence is not in itself a finding about the gene and the disease.
COVID-19 (continued). "A logistic regression model combined with age, respiratory rate (RR), lactate dehydrogenase (LDH), D-dimer, and albumin was selected to predict the occurrence of moderate COVID-19." (PMID 38226092, 2023). "As also presented in our results, serum lactate dehydrogenase (LDH) and albumin are also prognostic markers in COVID-19." (PMID 37629114, 2023). "Reduced total calcium levels in COVID-19 patients can sometimes be attributed to low serum albumin levels." (PMID 37760804, 2023). "We found a significant impact of mild COVID-19 on the renal function as determined by significantly higher levels of SCr and lower levels of serum albumin at the time of diagnosis of the infection." (PMID 35877031, 2023). "The significance of predictive parameters in our study indicates the existence of an important combined role of vitamin D, albumin, and D-dimer in the early diagnosis of the most severe patients suffering from COVID-19." (PMID 37109161, 2023). "The increase in albumin levels indicates that patients in the peri-COVID-19 group had an improved nutritional status due to better dietary intake." (PMID 37692622, 2023). "Patients in the peri-COVID-19 group had albumin levels 2.13% (95% CI: 0.88 to 3.39) higher than patients in the pre-COVID-19 group (P ≤ 0.001)." (PMID 37692622, 2023). "Other factors, such as ratio of lymphocytes, direct and total bilirubin, albumin, transferrin, pH, protein in the pleural fluid, and SpO2, showed very low RR values (0.17 to 0.48), which fits with their inverse correlation with COVID-19 severity." (PMID 36668902, 2023). "The fibrinogen-to-albumin ratio level has been proposed as a marker in coagulopathy and a good indicator of COVID-19 progression." (PMID 37372959, 2023). "After modeling patients aged ≤66 years, we found that age, D-dimer, LDH, respiratory rate, and albumin still had the highest characteristic weights in the model, and the model had better efficacy in predicting moderate COVID-19 with higher AUC values." (PMID 38226092, 2023). "Increased levels of vitamin D were accompanied by higher levels of albumin in patients with COVID-19." (PMID 37109161, 2023). "That its flux down the KP is likely to be enhanced in COVID-19 is strongly suggested by the reported decrease in plasma [albumin] and increase in [NEFA]." (PMID 37486805, 2023). "In that study, they found AUC for CRP, procalcitonin, LDH, D-dimer, and albumin in the detection of severe COVID-19 patients to be 92%, 89%, 84%, 83%, and 82%, respectively." (PMID 36919085, 2023). "The ratio of ferritin to albumin (FAR) has been proposed as a novel prognostic indicator for COVID-19." (PMID 37817258, 2023). "Infection is associated with a low circulating [albumin] and a raised [NEFA], the influence of which on production of Kyn metabolites in inflammatory conditions, including COVID-19, should be assessed." (PMID 37486805, 2023). "At the same time, COVID-19-related liver damage impairs albumin synthesis, making an imbalance between its synthesis and degradation." (PMID 37873785, 2023). "On admission, patients in the intensive COVID-19 sector had serum albumin levels above 3.5 g/dL in both groups." (PMID 36982882, 2023). "Because higher levels of ALT and albumin have been observed in patients with COVID-19, tests for liver abnormalities can be considered indicators of infection." (PMID 36968904, 2023). "Decreased albumin levels were present in both COVID-19 patient groups when compared to controls (p < 0.001), with the lowest levels in ICU patients." (PMID 37629114, 2023). "Elevated levels of these enzymes indicate severe liver damage that increases the risk of mortality among COVID-19 patients, while the levels of other liver proteins, such as albumin, decrease in COVID-19 patients." (PMID 36671484, 2023). "The most important markers which were useful in COVID-19 diagnosis are Eosinophil, Albumin, T. Bilirubin, ALP, ALT, AST, HbA1c and TWBC." (PMID 37436038, 2023).
COVID-19 (continued). "The presented data on serum albumin levels (mean ± SE) measured between 24 and 48 h before exitus in COVID-19 patients (**)." (PMID 36982882, 2023). "Based on the obtained results, we suggest that the stable nitroxide radical 3-Maleimido-PROXYL can be successfully used as a marker to study oxidized albumin levels in COVID-19." (PMID 36982882, 2023). "COVID-19 patients had reduced hemoglobin, lymphocyte count, eosinophil count, and serum albumin values." (PMID 36828545, 2023). "The double-integrated spectra of 3-Maleimido-PROXYL radical showed a low degree of connectivity due to high levels of oxidized albumin in COVID-19 patients." (PMID 36982882, 2023). "In the univariate analysis, age, BMI, lymphocytes, neutrophils, LDH, CRP, ferritin, D-dimer, albumin, AST, ALT, and creatinine were significantly associated with severe COVID-19." (PMID 36653462, 2023). "The top five variables on the obtained model feature weights were selected as age, D-dimer, LDH, respiratory rate, and albumin, and their AUC values for the prediction of moderate COVID-19 were 0.714, 0.591, 0.589, 0.605, and 0.634." (PMID 38226092, 2023). "Simple and quick-to-obtain biochemical parameters such as red cell distribution width (RDW) and CRP-to-albumin ratio (CAR) provide additional prognostic information to COVID-19 prognostic scores." (PMID 36864814, 2023). "In 288 patients with COVID-19, we analyzed the differences in the values of D-dimer, albumin, and vitamin D in relation to the severity of the clinical picture and the outcome of the disease." (PMID 37109161, 2023). "In a meta analysis study analyzing sixty-seven studies with a total of 19,760 COVID-19 patients, it was concluded that low albumin concentration were significantly lower in patients with severe disease." (PMID 37497238, 2023). "In fact, the administration of albumin supplementation to COVID-19 patients allowed for anticoagulant therapy." (PMID 37954188, 2023). "In our analysis, low albumin and a reduction in albumin level were both found in patients with COVID-19, especially those with severe pneumonia." (PMID 37501590, 2023). "Our results show that decreased levels of vitamin D and albumin, in combination with elevated levels of D-dimer, indicate a more severe clinical picture and a fatal outcome due to COVID-19." (PMID 37109161, 2023). "The most important markers that were useful in COVID-19 diagnosis are eosinophil, albumin, T. bilirubin, ALP, ALT, AST, HbA1c and TWBC." (PMID 37436038, 2023). "Our results mirrored the ratio of oxidized to reduced albumin levels in severe COVID-19 patients, showing a significant correlation between the parameters of the EPR spectrum of the nitroxides and the severity of the disease." (PMID 36982882, 2023). "In many clinical settings, hypoproteinemia is associated with increased severity and mortality, which is consistent with our findings: moderate COVID-19 cases had lower albumin levels than the mild type of COVID-19." (PMID 38226092, 2023). "The obtained result indicates that an increase in the value of serum albumin by 1 g/L reduces the probability of developing a severe form of COVID-19 by 24.1%, provided that the values of all other parameters in the model are equal." (PMID 37109161, 2023). "Critically ill patients on VV-ECMO also had significantly lower values of albumin when compared to both severe and critical COVID-19 groups (p < 0.001 and p < 0.050, respectively)." (PMID 36617343, 2023). "In the moderate-severe group, the closest neighbors of COVID-19 severity were ferritin, fibrinogen, albumin, quantity of lymphocytes, scoring index of chest x-ray, WBC count, LDH, and quantity of neutrophils." (PMID 36668902, 2023). "Reduced values of vitamin D and albumin, in combination with elevated values of D-dimer, can be timely indicators of the development of a severe clinical picture and death due to COVID-19." (PMID 37109161, 2023).
COVID-19 (continued). "A significant weak inverse correlation between viral load as determined by COVID-19 CT and serum albumin was found (r = – 0.317, P = 0.028)." (PMID 35877031, 2023). "Reduced values of vitamin D and albumin and elevated values of D-dimer can quickly indicate the development of a severe clinical picture and death due to COVID-19." (PMID 37109161, 2023). "The administration of albumin intravenously to COVID-19 patients enhanced hemodynamics and resulted in a reduction in the plasma concentration of D-dimer, a primary indicator of thromboembolism." (PMID 37954188, 2023). "More importantly, this study confirms that decreased albumin and A/G ratio can serve as predictive indicators for the progression to severe COVID-19." (PMID 38145047, 2023). "Clinical trials and extensive studies on infusions of serum albumin in COVID-19 patients are urgently needed." (PMID 36077496, 2022). "The best model to predict COVID-19-related death became the one including albumin and TBIL, with albumin significance at the level of OR 0.229, p < 0.0001, and TBIL OR 1.657, p = 0.001." (PMID 35956107, 2022). "The reported studies looking at albumin as a predictor of mortality for COVID-19 patients included a very limited number of severe COVID-19 patients." (PMID 35160039, 2022). "Age, SpO2, albumin and D-dimer were demonstrated as independent predictors for mortality in patients with COVID-19 in different previous studies." (PMID 35350866, 2022). "The potential utility of albumin therapy in COVID-19 patients was recently described by an Italian group." (PMID 35502320, 2022). "We aimed to assess the combined role of vitamin D and albumin serum levels as predictors of COVID-19 disease progression." (PMID 35182287, 2022). "We found significantly higher levels of AAT and M65 but lower ALB in severe compared to moderate COVID-19 patients." (PMID 36514048, 2022). "We screened the COVID-19 samples in three steps: initially, 3492 COVID-19 positive samples were selected with variant levels of LDH, CRP, D-dimer, lymphocytes, AST, ALT, CK, albumin, and procalcitonin compared to the reference values." (PMID 35997388, 2022). "Lower albumin, magnesium and calcium are also found in the serum of patients affected by COVID-19 than in healthy subjects, underling that the addition of calcium and magnesium may help to reduce the consequences of COVID-19, such as chronic fatigue-syndrome-like and physiosomatic symptoms." (PMID 35911401, 2022). "Previous studies investigated predictors of COVID-19 exacerbation according to chest CT scans and showed factors such as serum albumin, C reactive protein (CRP), and coronary plaque burden as predictors of COVID-19 outcomes." (PMID 35958125, 2022). "In other studies, liver functions and albumin levels have been defined as important determinants of mortality in patients with severe COVID-19." (PMID 36052658, 2022). "These verdicts propose that severe SARS-CoV-2 infection in COVID-19 patients can increase blood viscosity by modulating fibrinogen, albumin, lipoproteins, and erythrocyte deformability and aggregations." (PMID 35783600, 2022). "Infusions of human albumin solution can reduce the more severe or life-threatening events that take place in COVID-19 patients." (PMID 36077496, 2022). "This strengthens previous data that found albumin-based immunonutritional scores such as PNI have a high prognostic value for COVID-19 disease severity." (PMID 36296963, 2022). "When combining LDH with albumin as a measure of nutritional status, the LDH-to-albumin ratio shows a promising prediction of mortality in KTR with COVID-19." (PMID 36556433, 2022). "The ALB levels of patients with severe COVID-19 were lower than those of patients with mild cases or good outcomes." (PMID 36326681, 2022). "High levels of ROS lead to impaired structural flexibility of albumin in critically ill patients with COVID-19." (PMID 36552520, 2022).
COVID-19 (continued). "Referral (n = 801) and validation (n = 754) groups were randomly performed to prove that native albumin data can be used to predict outcomes of COVID-19 patients." (PMID 35160039, 2022). "The correlations observed between the level of albumin or AOPPs with inflammatory parameters or surrogate markers of COVID-19 severity as well as with lung HRCT score confirm the involvement of oxidative stress in COVID-19." (PMID 36077496, 2022). "Although some of the variables considered exceeded their importance, each of them turned out to be significant, so they can be independent predictors of death in the course of COVID-19, working better when assessed in combination with albumin." (PMID 35956107, 2022). "Elevated LDH and albumin in the airways provides further evidence of ongoing cell death and damage to respiratory barrier integrity post-COVID-19." (PMID 35151371, 2022). "It is well known that serum albumin concentration is negatively influenced by acute diseases, and in COVID-19 patients, low albumin levels have been related to poor prognosis." (PMID 36362858, 2022). "Albeit within the reference range, the levels of ALB were significantly lower, but CP were significantly higher in COVID-19 patients as compared to healthy controls." (PMID 36514048, 2022). "In our cohort, GMVs of olfactory pathway regions were negatively correlated with the CSF/plasma albumin ratio, CSF leukocytes and protein levels in COVID-19 patients." (PMID 36351919, 2022). "Chlorine-induced albumin damage appears to play a key role in exacerbating respiratory problems in COVID-19 patients." (PMID 36077496, 2022). "One study revealed that SARS-CoV-2 needs and utilizes albumin, so immediate albumin therapy is recommended for severe COVID-19." (PMID 36676691, 2022). "The critical COVID-19 group had lower total protein, albumin, calcium, and lymphocyte levels and higher lactic dehydrogenase, blood urea nitrogen, and d-dimer levels than the non-critical group." (PMID 36035409, 2022). "COVID-19 enters the cholangiocytes through ACE2-R and causes direct damage with liver enzyme alteration, including albumin, GGT, ALT, and AST." (PMID 36676691, 2022). "A mild to moderate increase in acute-phase proteins (APPs) and a decrease in serum albumin levels are detected in hospitalized COVID-19 patients." (PMID 35336843, 2022). "Reduction in Albumin level during the hospital stay, particularly in COVID-19 cancer patients should be considered as a predictor of mortality." (PMID 35350203, 2022). "Dynamic monitoring of serum albumin is therefore necessary and should be performed during treatment of patients with COVID-19 as a tool to assess the prognosis of infection." (PMID 35736249, 2022). "It has been claimed that low serum albumin is associated with nutritional risk in ESRD, atrial fibrillation, and critically ill COVID-19 patients' disease severity and outcome." (PMID 35865866, 2022). "BAR and FAR are constructed based on values of fibrinogen, albumin and urea, which are altered in patients with COVID-19." (PMID 36006242, 2022). "Low albumin levels in critically ill patients with COVID-19 (HAS < 3.5 g/dL) correspond to higher DIA values." (PMID 36552520, 2022). "The authors found a persistently elevated CSF/blood-albumin ratio, CSF total protein levels, CSF lactate levels, and inflammatory cytokines in COVID-19 patients." (PMID 36340780, 2022). "There is a potential role for early albumin and calcium supplementation to prevent lipotoxicity in COVID-19." (PMID 35502320, 2022). "We aimed at examining both the incidence and extent of different lung perfusion abnormalities as well as the relationship between them on Tc-99m macroaggregated albumin (MAA) perfusion-only SPECT/CT scans in COVID-19 patients." (PMID 35763163, 2022). "Hemoglobin and serum albumin levels were significantly decreased in the severe, mild, and asymptomatic COVID-19 groups compared to normal volunteers (p < 0.001)." (PMID 36560587, 2022).
COVID-19 (continued). "The achieved covalent binding allows the assessment of albumin conformational changes in critically ill patients with COVID-19 and shows excellent agreement between the parameters of the EPR spectrum of the radical and perturbations in the albumin structure." (PMID 36552520, 2022). "This issue is partly addressed by the human study showing that COVID-19 patients receiving albumin and anticoagulation had improved survival than those who received anticoagulation only." (PMID 35502320, 2022). "Consistently, a recent meta-analysis identified a low circulating serum albumin level as an independent predictor of poor prognosis in patients with COVID-19." (PMID 35885582, 2022). "Our study proved that patients with PIMS present a significantly higher level of albumin in comparison to COVID-19 group." (PMID 36138657, 2022). "This analysis also confirmed the association between COVID-19 mortality and low Hb concentration, high WBC count, high neutrophils, low albumin, low total proteins and high BUN." (PMID 35584141, 2022). "Serum albumin was higher and total bilirubin, aspartate aminotransferase, and alanine aminotransferase were lower in the COVID-19 cases compared with controls." (PMID 35168193, 2022). "Compared to the asymptomatic and mild groups, the severe COVID-19 patient group had significantly lower lymphocyte percentages and albumin levels (p < 0.001)." (PMID 36560587, 2022). "White blood cell (WBC), urea, creatinine, LDH, ferritin, and D-dimer levels increased in those who died from COVID-19, while albumin and CRP levels decreased." (PMID 36060378, 2022). "COVID-19 patients with pneumonia had decreased levels of lymphocytes and albumin, while ALT, RBC, platelets, monocytes, eosinophils, ferritin, troponin-I, blood urea, and creatinine were not significantly changed compared to COVID-19 patients." (PMID 35997388, 2022). "In the in vitro study, we demonstrated that native albumin binds the COVID-19 spike protein S1 subunit (the recombinant S1 subunit used contained the spike protein amino-acid sequence from 16 to 690 of the spike protein)." (PMID 35160039, 2022). "A low albumin level detected at the emergency department was found to be a potential marker to predict severe infection and mortality at 30 days in patients with COVID-19." (PMID 36464717, 2022). "One Chinese study published in 2021 evaluated serum albumin as a possible predictor for COVID-19 outcome." (PMID 36676691, 2022). "The patients from the COVID-19 group had lower total calcium levels (p < 0.001) and serum albumin levels (p < 0.001), while levels of albumin-adjusted calcium were similar to the reference group (p = 0.06)." (PMID 35893730, 2022). "The analysis confirmed the association between COVID-19 in-hospital mortality and low Hb, high WBC, high neutrophils, high BUN and low albumin levels." (PMID 35584141, 2022). "Both fibrinogen-to-albumin ratio (FAR) and blood urea nitrogen-to-albumin ratio (BAR) are potential alternatives to predict severity in COVID-19 patients." (PMID 36006242, 2022). "Albumin concentration analysis showed a significant decrease in COVID-19 patients with severe conditions compared to the control group (p = 0.0004)." (PMID 35842705, 2022). "Concentrations of NLR, CRP, D-dimer, fibrinogen, ferritin, albumin, and total protein of the control group were significantly different than their counterparts in both mild-moderate and severe COVID-19 patients." (PMID 36627978, 2022). "When compared to controls, COVID-19 patients independently on their disease severity had lower plasma levels of ALB (by 42%) but significantly higher levels of AGP (by 2.4-fold), AAT (by 1.9-fold), CP (by 1.4-fold), HP (by 3.8-fold), and hs-CRP (by 52-fold)." (PMID 36514048, 2022). "A systematic review and meta-analysis of 23 studies found that in patients with severe COVID-19, high values of procalcitonin, C-reactive protein, D-dimer, and lactic dehydrogenase were found, as well as low values of albumin." (PMID 35601226, 2022).